IL6 (interleukin 6)
Diseases named in the same sentence as IL6 in open-access papers (continued):
Sharing a sentence is not in itself a finding about the gene and the disease.
Autoimmunity (continued). "IL-1β and IL-6 have a pathological effect on chronic inflammation and autoimmunity." (PMID 35548349, 2022). "Moreover, IL-1β and TNF-α both can activate the generation of pro-inflammatory IL-6 and then contributes to the pathogenesis of various diseases, such as inflammation, autoimmunity, and malignancies." (PMID 36139256, 2022). "This proposition suggests that the increase in OPG in both hypothyroid and hyperthyroid patients may be due to the significant effect of IL-6 and autoimmunity." (PMID 36161625, 2022). "Indeed, GM-CSF was reported to mediate autoimmunity by enhancing IL-6–dependent survival of antigen specific CD4+ T cells and promoting generation and maintenance of Th17 cells in vivo." (PMID 36059463, 2022). "Our data thus indicate how IL-6 signaling may destabilize the Treg compartment and potentially these markers could be useful to track efficacy of therapies in autoimmunity." (PMID 35911690, 2022). "IL-6 serum levels are markedly increased in mice with autoimmunity, and human patients with SLE." (PMID 36389691, 2022). "Moreover, TNF-α, IL-1β, and IFN-γ can also activate the generation of pro-inflammatory IL-6 which contributes to the pathogenesis of various diseases, such as inflammation, autoimmunity, and cancers." (PMID 36204610, 2022). "Among them, IL-6 targets can not only induce B lymphocytes to proliferate, differentiate and secrete corresponding antibodies, but also promote the proliferation and activation of T lymphocytes, thus participating in anti-infective immunity and autoimmunity." (PMID 35935817, 2022). "As recently reported, IL-6 present in the microenvironment lowers the immune response induced by chemotherapy, suggesting that targeting IL-6 may, on one hand, suppress autoimmunity, while on the other it potentiates antitumour response." (PMID 35806034, 2022). "In addition, we evaluated the impact of two supplementary cytokines, IL6 largely described as a mediator of inflammation and autoimmunity, and granulocyte macrophage colony-stimulating factor (GM-CSF) involved in chronic inflammation." (PMID 34774107, 2021). "Although the expression levels of these inflammation cytokines induced by TBI are gradually suppressed by autoimmunity in the vehicle control group over time, especially 7 days post injury, there are still significant differences in IL-1β and IL-6 levels between the Sham and TBI groups." (PMID 33414464, 2021). "In addition, we evaluated the impact of IL1β and IL6 largely described as mediators of inflammation and autoimmunity, and GM-CSF, involved in chronic inflammation." (PMID 34774107, 2021). "Among these cytokines, therapeutic approaches targeting excessive inflammation caused by IL-6 interaction with its cellular receptor IL-6R have been under investigation using IL-6 antagonists such as tocilizumab and sarilumab used in the treatment of autoimmunity." (PMID 34552938, 2021). "In addition, IL-6 can inhibit the proliferation of Tregs and promote the development of autoimmunity." (PMID 33882880, 2021). "However, continuous dyssynthesis of IL-6 has a pathological role in chronic inflammation and autoimmunity." (PMID 34790229, 2021). "We show for the first time that LIFNano-CD4 (i) cross the BBB; (ii) reduce pathogenic levels of IL-6 that accumulate behind the BBB during demyelinating autoimmunity; and (iii) are non-toxic at efficacious i.v. doses in a formal preclinical SAD trial." (PMID 35047909, 2021). "IL-6 is an important pro-inflammatory cytokine that regulates both acute and chronic inflammatory responses and has distinctive roles in driving inflammatory processes, autoimmunity, and endothelial cell dysfunction." (PMID 35366257, 2021). "Interestingly, meningeal B cells exhibited a strong plasma cell response (Xbp1high), and a pro-inflammatory activation state characterized by expression of genes related to CNS inflammation and autoimmunity, including Il6, Ifnγ, Ifnγr, Il23, and Tnfα." (PMID 33277355, 2021).
Autoimmunity (continued). "IL-6 is produced rapidly and briefly in response to infection and tissue damage, but the persistent dysregulation of IL-6 synthesis plays a pathological role in chronic inflammation and autoimmunity." (PMID 34531872, 2021). "Differentiation of Th17 cells is dependent on interleukin 6 (IL-6) and transforming growth factor β (TGFβ), whereas their full maturation depends on IL-1β and IL-23, possibly favoring their pathological activity in the induction of autoimmunity." (PMID 33542719, 2020). "Homocysteine may mediate melanocyte destruction via increased oxidative damage, interleukin-6 production, and tyrosinase inhibition, triggering autoimmunity and nuclear factor κB activation, and then contributing to the occurrence of vitiligo." (PMID 33093609, 2020). "The results demonstrated the colocalization of DAPI and hCD90 with the expression of BDNF, TGF-β1, GFAP, and interleukin-6 (IL-6) in hAFSCs, indicating that hAFSCs could produce neurotrophic factors and possess anti-autoimmunity and anti-inflammatory effects." (PMID 32572272, 2020). "Thus, the present study for the first time demonstrates the rationale for this treatment and the pathophysiology of IL-6 signaling in PD-1 signal inhibition-provoked autoimmunity." (PMID 33060784, 2020). "IL-6 has pleiotropic effects on inflammation, immune response, and hematopoiesis, but dysregulated synthesis of IL-6 plays a pathological effect on chronic inflammation and autoimmunity." (PMID 33349270, 2020). "In this regard, the increased IL-6 production observed with vitamin D treatment may also influence T cell differentiation to a phenotype that would be undesired in the context of autoimmunity." (PMID 33343562, 2020). "Taken together, these results imply that IL-6 might be a crucial inducer of paraneoplastic autoimmunity, although additional studies are required to substantiate the relationship between IL-6 and autoimmunity in PNP." (PMID 31214197, 2019). "Through the analysis of the VEGF165-related pathway, we found three pathways related to autoimmunity, including IL-6 signaling, IL-8 signaling and clathrin-mediated endocytosis signaling, the IL-6 signaling pathway is most relevant compared to the other two pathways." (PMID 31354478, 2019). "IL-6, derived from Th2 cells, drives the stimulation of B-cell and T-cell differentiation into Th2 cells but induces pathological effect on chronic inflammation and autoimmunity when dysregulated continual synthesis." (PMID 31466385, 2019). "However, the dysregulated expression of IL-6 can lead to development of chronic inflammation or abnormal autoimmunity." (PMID 30642099, 2019). "Therefore, it is likely that increased IL-6 production by Btk-overexpressing B cells is a major driver of autoimmunity in CD19-hBTK mice." (PMID 30761150, 2019). "However, persistent IL-6 production or overexpression can lead to the development of various diseases particularly those related to chronic inflammation and autoimmunity." (PMID 30258443, 2018). "The redundancy and possible additive or synergistic effects of the IL-6 and IL-21 pathways, as well as the therapeutic potential of combined pathway blockade in Th17-driven autoimmunity remain unclear." (PMID 28158305, 2017). "In the context of autoimmunity, our data demonstrate that several major determinants of T cell encephalitogenicity, including T-bet, IL-12, and IL-6, skew IL-7Rα/PD-1 balance towards IL-7Rα, favoring an encephalitogenic phenotype of myelin-specific CD4 T cells with enhanced effector function." (PMID 27912762, 2016). "Interestingly, in one of these lines, blockade of IL-6 also suppressed the development of autoimmunity, indicating that elevated levels of more than one cytokine are required to trigger SLE." (PMID 27807192, 2016). "Furthermore, following ex vivo stimulation, the levels of IL-6–producing splenic B cells, which are proposed to be an important driver of autoimmunity in mice 25, were reduced by in vivo exposure to ES-62." (PMID 25546822, 2015).
Autoimmunity (continued). "Finally, reduced disease severity after elimination of B cells secreting IL-6 in two EAE models as well as in patients with relapsing remitting MS supports a destructive role for IL-6 during CNS autoimmunity." (PMID 25896970, 2015). "IL-6 is well known as a promoter of Th17 differentiation in settings such as autoimmunity in mice." (PMID 24185641, 2014). "Although IL-1alpha; has not been directly linked to the autoimmunity elicited by pristane, it does induce expression of IL-6, which is required for pristane-induced hypergammaglobulinemia and the production of anti-DNA and anti-chromatin." (PMID 23557436, 2013). "IL-17A also contributes to autoimmunity by triggering a positive feedback loop via IL-6 induction." (PMID 24454477, 2013). "Moreover, IL-6 is involved in autoimmunity by altering the balance of Th17 cells by inducing the differentiation of Th17 cells from naïve CD4+ T cells." (PMID 23133751, 2012). "Interleukin-6 (IL-6) is an immunoregulatory cytokine that plays an important role in autoimmunity." (PMID 23424706, 2012). "It is possible that leptin, CRP, or IL-6 levels may be confounded by ethnic differences in inflammatory or autoimmune conditions; however, this is unlikely given that the women in this study were apparently healthy and relatively young." (PMID 21331287, 2011). "In addition to its role in the acute phase response, IL-6 has diverse roles in driving chronic inflammation, autoimmunity, endothelial cell dysfunction, and fibrogenesis." (PMID 21941555, 2011). "In conclusion, IL-6 participates in both the inflammation and autoimmunity of RA patients." (PMID 22046525, 2011). "Therefore, viral induction of disease follows a different disease pathogenesis with a more complex immune response in which cytokines, such as IL-6, have varied specific roles compared to experimental models of autoimmunity." (PMID 19587788, 2009). "IL-6 is a pleotropic cytokine that acts during both pro- and anti-inflammatory responses and has been observed in the context of infection, inflammation and autoimmunity." (PMID 19587788, 2009). "Recent findings underscore the pivotal role of key cytokines and chemokines – such as IL-17, TNF-α, IL-6, BAFF, and CXCL13 – as well as specific autoantibodies (e.g. ACPA, ANA) that not only drive local inflammation but may also perpetuate systemic autoimmunity in susceptible individuals." (PMID 41257445, 2025). "In particular, Interleukin-6 (IL-6) is a prototypical pleiotropic cytokine polypeptide secreted into the serum by T cells and macrophages, which plays an important role in many bodily processes, such as chronic inflammation, acute phase response, autoimmunity, and fibrogenesis." (PMID 40422059, 2025). "Furthermore, IL-6 is a crucial mediator in the differentiation of Th17 cells and in the suppression of regulatory T cells, which can exacerbate inflammation and potentially lead to autoimmunity." (PMID 40943602, 2025). "Therefore, targeting the IL-6/IL-21/SOCS2/STAT5 pathways to restore NK-cell function against autoimmunity may hold therapeutic promise for MG." (PMID 39346912, 2024). "While, IL-6 trans-signalling and trans-presentation may be a more potent inducer of autoimmunity than classic signalling, our finding that blood IL6R and IL6ST expression are associated with increased risk of type 1 diabetes may be explained by any of the three signalling modalities." (PMID 39271518, 2024). "While expression of IL-6 is tightly regulated by transcriptional and post-transcriptional mechanisms, in situations where the synthesis of IL-6 is chronically elevated, the inflammatory cascades that ensue lead to the pathological effects of chronic inflammation and autoimmunity." (PMID 37841263, 2023). "Furthermore, the role of IL-6 in autoimmunity has been suggested." (PMID 37762312, 2023).
Autoimmunity (continued). "Despite these encouraging results, efforts to apply IL-6 or IL-6R blockade prospectively with therapeutic intent in clinical trials have lagged behind preclinical data, possibly due to resistance to repurpose these drugs from autoimmunity into the oncology setting." (PMID 36881480, 2023). "IL-6 plays several roles in the development of myocarditis, including decreasing cardiac contractility, increasing expression of adhesion molecules for natural killer cells (NK), lymphocytes, and macrophage recruitment, and mediates the development of autoimmunity." (PMID 36851240, 2023). "In addition, a prior study demonstrated that targeting the phosphorylation and degradation of Arid5a could facilitate the release of IL-6, consequently exerting a critical role in autoimmunity." (PMID 35725649, 2022). "Moreover, the increase in cancer cell IL-6 expression from combination therapy as well as the role of Th17 in autoimmunity suggests that IL-17 blockade could potentially ameliorate the observed clinical adverse events owing to immune checkpoint blockade." (PMID 33972557, 2021). "In this sense, the objective of the present study was to identify polymorphisms in important mediators of the immune response (FOXP3, IFNG, IL6, IL8, IL10, MBL2, CRP, TGFΒ1 and TNFA) in association with ANAs, which could contribute to the development of autoimmunity in hepatitis C." (PMID 32743104, 2020). "In line with this hypothesis, gene knockout studies, aimed at investigating the miR-146a function, showed that deficiency of this miRNA may lead to an excessive IL-6 and TNF-α production, hyperresponsiveness to bacterial lipopolysaccharide (LPS), chronic inflammation, and spontaneous autoimmunity." (PMID 32210951, 2020). "In addition, Ginsenoside Rd displayed the therapeutic function to EAE specifically by modulating inflammation and autoimmunity, via the downregulation of related proinflammatory cytokines IL-6 and IL-17, upregulation of inhibitory cytokines TGF-β and IL-10, and regulation of Treg/Th17 imbalance." (PMID 33380901, 2020). "The serum levels of pro-inflammatory and immunomodulatory cytokines such as IL-1β, IL-6, IL-8, IL-10, IL-17, and IL-15 were used as secondary study endpoints as they provide a strong evidence of the efficacy of the hMSCs administration inmodulating autoimmunity." (PMID 30254638, 2018). "Interestingly, in mice B cell derived IL6 potentiated Th17 cells, prompting the authors to speculate that B cell depletion ameliorates autoimmunity in this setting through ablation of IL6-producing B cells." (PMID 26047509, 2015). "Studies have shown that IL23 promotes inflammatory responses by inducing the production of IL17, IL6, IL8, and tumor necrosis factor-α and that it regulates the amplification and the stability of Th17 lymphocytes, which are associated with strong pro-inflammatory responses and severe autoimmunity." (PMID 23840727, 2013). "In addition, IL-6 may contribute to the induction and maintenance of the autoimmunity through B-cell activation and Th17 cell differentiation." (PMID 22046525, 2011). "Moreover, IL-6 is involved in autoimmunity by altering the balance between Th17 cells and Treg." (PMID 22046525, 2011). "However, the function of IL-6 during viral-mediated autoimmunity has yet to be elucidated." (PMID 19587788, 2009). "TO reduces TNF-α, IL-6, and IgE; and induces IFN-γ levels, which makes it useful in the treatment of allergies, autoimmunity, and infections." (PMID 41601978, 2026). "It has been shown that IL-6 can strongly inhibit the TGFβ-mediated differentiation of naïve CD4 T cells into regulatory T cells, which inhibit autoimmunity and protect against tissue injury." (PMID 40649269, 2025). "Interplaying between IFN-γ and IL-6 is required for the expression of IFN-γ-regulated genes, which is a key part of autoimmunity." (PMID 39981245, 2025). "The interaction between IL-6 and IFN-γ is required for the expression of IFN-γ-regulated genes in autoimmunity." (PMID 39981245, 2025).
Autoimmunity (continued). "Previous studies have demonstrated that IL-6 regulates and promotes CD4+ T cell proliferation, thereby creating an exaggerated immune response and thus leading to autoimmunity and the development of SLE." (PMID 40429614, 2025). "Extensive research has confirmed the pathological roles of the IL-6/JAK2/STAT1/3 signaling pathway in inflammation, autoimmunity, and cancer, as well as its involvement in the pathogenesis of various rheumatic diseases." (PMID 40170729, 2025). "IL-6 is considered one of the most prominent cytokines of the SASP and a determinant for the development of autoimmunity and neuroinflammation, because IL-6 is involved in MS immunopathogenesis." (PMID 38928437, 2024). "IL-5, IL-6, IL-13, IL-17, IL-23, and TNF-α are targetable with biologics developed for spontaneous autoimmunity, and our data broadly support the prospective investigation of these inhibitors for patients with irAEs." (PMID 39403935, 2024). "Elevated levels of pro-inflammatory cytokines such as IL-6, TNF-α, and IL-1β are frequently observed in adenomyosis, creating an environment conducive to autoimmunity." (PMID 39518312, 2024). "Another study showed a dependency of accelerated autoimmunity and beta cell destruction on increased IFN-γ, IL-12, and IL-17 and decreased IL-4, IL-6, and IL-13 in pediatric patients with T1D." (PMID 37893217, 2023). "Meanwhile, in the presence of IL-6, TGF-β1 has been implied to prompt the differentiation of T helper cells, contributing to escalated inflammation and exacerbating autoimmune conditions." (PMID 38136437, 2023). "It is widely recognized that proinflammatory cytokines such as interleukins 1 (IL-1), interleukin 6 (IL-6), and tumor necrosis factor alpha (TNF-α) play a crucial role in promoting autoimmunity, persistent inflammation, and joint damage." (PMID 38256854, 2023). "Th17a T helper cells are derived from T helper cell 0 (Th0) when stimulated with IL6 and IL23, and are a potent source of inflammatory IL-17, playing an important role in autoimmunity in humans." (PMID 35327670, 2022). "In IA such as RA, various cytokines such as IL-1 (interleukin), IL-6, IL-8, and tumor necrosis factor-alpha (TNF-alpha) contribute to inflammation and autoimmunity leading to the destruction of joints." (PMID 36321010, 2022). "The autoimmunity status was overactivated in FDD patients, and serum IL-6 and IL-17 levels had direct impact on the HAMD score." (PMID 35615531, 2022). "Similar to IL-6, PGF increased IL-17 production but suppressed the formation of regulatory T cells, leading to autoimmunity in the form of autoimmune encephalomyelitis and collagen-induced arthritis." (PMID 36046049, 2022). "Here we report that a cascade involving IFN-I, IL-6 and B cells promotes TH17-mediated neuro-autoimmunity." (PMID 32503977, 2020). "Proinflammatory agents (e.g., IL-1, IL-6, and TNF-α) appear to have a substantial role in the control of autoimmunity, and overproduction of cytokines can provoke some autoimmune disorders." (PMID 28611508, 2017). "To study possible contributions of IL6 to the BXSB.Yaa disease, we first compared levels of IL6 in sera from male BXSB.Yaa to levels for female BXSB mice, which develop a mild form of autoimmunity when older than 1 year." (PMID 27050763, 2016). "Therefore, it is possible that the notable peripheral autoimmunity in adult IL-2KO mice may be a more significant factor that could affecting brain function and cognitive behavior (e.g., feedback from proinflammatory cytokines such as IL-1 and IL-6)." (PMID 25961067, 2015). "Th17 cell is a key effector in the immune response and play critical roles in the development of autoimmunity by producing IL-17 and, to a lesser extent, TNF-α and IL-6." (PMID 23345934, 2012). "For example, abnormally elevated concentrations of IL-6 could possibly saturate the IL-11 receptors, leading to dysregulated STAT3 activation, promoting chronic inflammation and autoimmunity." (PMID 41333011, 2025).